GALNT1 (polypeptide N-acetylgalactosaminyltransferase 1)
Description:
Catalyzes the initial reaction in O-linked oligosaccharide biosynthesis, the transfer of an N-acetyl-D-galactosamine residue to a serine or threonine residue on the protein receptor. Has a broad spectrum of substrates such as apomucin-, MUC5AC-, MUC1- and MUC2-derived peptides.
Synonyms: GalNAc-T1
Tractability: Antibody: UniProt places it where antibodies can reach, with medium confidence; UniProt predicts a signal peptide or a membrane-spanning region; its Gene Ontology location is reachable by antibodies, with medium confidence. PROTAC: ubiquitination databases record sites on it; its protein half-life has been measured; a small molecule that binds it is known.
Target class: Enzyme; Transferase
Gene: Protein-coding gene on chromosome 18 (35,580,892 to 35,713,370, forward strand). Ensembl gene ENSG00000141429.
Subcellular location: Golgi apparatus, Golgi stack membrane (Polypeptide N-acetylgalactosaminyltransferase 1); Secreted (Polypeptide N-acetylgalactosaminyltransferase 1 soluble form)
Pathways (Reactome):
Disease: Maturation of protein 3a
Metabolism of proteins: O-linked glycosylation of mucins
Vesicle-mediated transport: COPI-independent Golgi-to-ER retrograde traffic
Gene Ontology:
Molecular function: manganese ion binding; polypeptide N-acetylgalactosaminyltransferase activity
Biological process: protein O-linked glycosylation via N-acetyl-galactosamine; protein O-linked glycosylation; viral protein processing
Cellular component: Golgi apparatus; membrane; perinuclear region of cytoplasm; endoplasmic reticulum membrane; endoplasmic reticulum-Golgi intermediate compartment membrane; Golgi membrane; extracellular region; Golgi cisterna membrane
Genetic constraint (gnomAD): Loss-of-function variants: 10 observed, 47.29 expected, observed/expected ratio (o/e) 0.21, 90% interval 0.13 to 0.36. The upper end of that interval is the gene's LOEUF score, 0.36, which puts it in group 1 of 6, group 1 being the genes least tolerant of losing a copy. Missense variants: 365 observed, 547.34 expected, observed/expected ratio (o/e) 0.67, 90% interval 0.61 to 0.73. Synonymous variants: 171 observed, 180.52 expected, observed/expected ratio (o/e) 0.95, 90% interval 0.84 to 1.08.
Homologues: Orthologues: chimpanzee GALNT1 (100% identical), macaque GALNT1 (100% identical), guinea pig GALNT1 (99% identical), dog GALNT1 (99% identical), pig GALNT1 (99% identical), rat Galnt1 (99% identical), mouse Galnt1 (98% identical), zebrafish galnt1 (91% identical), tropical clawed frog galnt1 (87% identical). Paralogues in human: GALNT13 (84% identical), GALNT6 (44% identical), GALNT10 (43% identical), GALNT3 (42% identical), GALNTL6 (42% identical), GALNT2 (42% identical), GALNT4 (41% identical), GALNT11 (40% identical), GALNT12 (39% identical), GALNT7 (39% identical), GALNT5 (38% identical), GALNT14 (38% identical), and 7 more.
Diseases named in the same sentence as GALNT1 in open-access papers:
GALNT1 is named in the same sentence as 36 diseases in open-access papers, as found by Europe PMC text mining. Sharing a sentence is not in itself a finding about the gene and the disease. The quoted sentences say what the papers report.
bladder cancer (16 papers, 2014 to 2024). "Aberrant glycosylation resulting from mutations in GALNT1 was found to be involved in cardiac defects, and in melanoma, ovarian and bladder cancers." (PMID 27322213, 2016). "Bioinformatics analysis showed that GALNT1 is overexpressed in GC as well as other malignant tumors, including breast cancer, bladder cancer, and hepatocellular carcinoma." (PMID 36439876, 2022). "This study successfully identified a subset of bladder cancer stem cells that respond to GALNT1 siRNA and SHH inhibitors, providing a potential strategy for prevention and targeted treatment for recurrent bladder cancer." (PMID 35903544, 2022). "GALNT1 a glycotransferase have been identified by researchers to play a pivotal role in SHH instigation in CSC of bladder cancer." (PMID 33889547, 2021). "GALNT1 is increased in bladder cancer, C1GALT1C1 is increased in colorectal cancer and UGT8 is increased in breast cancer." (PMID 30038662, 2018). "In this manner, MAN2A1 has been reported to be altered in glioblastoma, GALNT1 is altered in bladder cancer, C1GALT1C1 is altered in colorectal cancer, and UGT8 is altered in breast cancer." (PMID 30038662, 2018). "In another report, a direct linkage between miR-129 and its putative targets SOX4 and GALNT1 have opened the possibility of a differential regulation of such genes in bladder cancer." (PMID 27322213, 2016). "Noteworthy, GALNT1‐mediated glycosylation is required for Shh activation in bladder cancer stem cells suggesting that proper glycosylation may play a role in Shh signaling function." (PMID 35068072, 2022). "LAG1 longevity assurance homolog 2 (LASS2) and Polypeptide N-acetylgalactosaminyltransferase 1 (GALNT1) were present in bladder cancer patients, whereas Rho guanine nucleotide exchange factor 39 (ARHGEF39) and Forkhead box protein O3 (FOXO3) were only found in controls." (PMID 30769831, 2019). "Moreover, GalNT1 can mediate the O-glycosylation of Sonic Hedgehog to promote signal activation in bladder cancer stem cells." (PMID 30038662, 2018). "Aberrant glycosylation resulting from GALNT1 involved in melanoma, ovarian, and bladder cancers." (PMID 29970122, 2018). "Our previous studies showed that glycopeptide‐preferring polypeptide GalNAc transferase 1 (ppGalNAc T1) mRNA was highly expressed in bladder tumor tissues and bladder cancer stem cells, and GALNT1‐positive staining in bladder cancer tissues was related to CD44 staining." (PMID 29577645, 2018). "In bladder cancer cells, expression of GALNT1-mRNA was higher by eleven-fold compared to normal cells, suggesting that hyperexpressed GALNT1 could be a novel marker for human bladder cancer." (PMID 27322213, 2016). "For example, by siRNA-mediated silencing of GALNT1, which control O-linked glycosylation activation of SHH signaling in CD44+ CSCs in bladder cancer to mediate stemness, the tumor growth was suppressed in a similar extent to cyclopamine in an orthotopic mouse model of bladder cancer." (PMID 33889547, 2021). "Moreover, uEVs from bladder-cancer patients showed to carry transcripts for LASS2 and GALNT1, involved in cancer progression and metastasis, and miR-1224-3p, miR-15b, and miR-135b, which correlate with a positive bladder cancer diagnosis, as well as the ratio miR-126:miR-152." (PMID 28638822, 2017). "Furthermore, lncRNA SNHG7 sponging miR216b promotes liver metastasis of CRC by up-regulating GALNT1, while down-regulation of SNHG7 can inhibit the phenotype of malignant bladder cancer." (PMID 36115953, 2022). "N-acetylgalactosaminyltransferase 1 (GALNT1) overexpression has been reported for the aberrant glycosylation of integrin α3β1 which leads to the change in the conformation of integrin and further induces focal adhesion kinase (FAK) activation in bladder cancer cells." (PMID 31450586, 2019).
colorectal cancer (12 papers, 2018 to 2025). A primary or metastatic malignant neoplasm that affects the colon or rectum. "Given that the TN antigen has been found to suppress the tumor immune microenvironment and promote colorectal cancer growth, we examined the relationship between GALNT1 expression levels and the tumor immune microenvironment in breast cancer." (PMID 37444599, 2023). "For example, SNHG7 is an oncogenic biomarker in COAD, and it interacts with miR-193b and positively regulates GALNT1 levels through sponging miR-216b in colorectal cancer." (PMID 35747807, 2022). "We found that GALNT1 expression is upregulated during EMT and has been confirmed to promote tumour proliferation and invasion in colorectal cancer." (PMID 37817210, 2023). "In several cancers, including colorectal cancer, prostate cancer, esophageal cancer, lung cancer and gastric cancer, lncRNA SNHG7 has been known as a potent oncogene by targeting GALNT1, Cyclin D1, FAIM2, p15 and p16." (PMID 30853913, 2019). "This analysis identified five glycosyltransferase genes, namely, ST6GAL1, GALNT6, HPSE, GALNT1, and GALNT7, expression of which was consistently upregulated or downregulated in MSI colorectal cancer tissues, cell lines, and single epithelial cells compared with MSS colorectal cancers." (PMID 40824763, 2025). "The abundance of GALNT1 and GALNT2 has been found to be significantly higher in colorectal cancer than that in normal epithelium, and high GALNT3 protein expression has been reported to be an indicator of tumor differentiation and a prognostic factor in colorectal cancer." (PMID 35692787, 2022).
hepatocellular carcinoma (5 papers, 2015 to 2022). A malignant tumor that arises from hepatocytes. "We found that GALNT1 is frequently up-regulated in hepatocellular carcinoma (HCC) and is associated with poor patient survival." (PMID 25730904, 2015). "For example, high expression of GALNT1 promotes the acquisition of a malignant phenotype in hepatocellular carcinoma via Epidermal Growth Factor Receptor signaling." (PMID 35003361, 2021). "For example, dysregulation of GALNT1 contributes to the malignant progression of hepatocellular carcinoma by modifying glycosylation of the epidermal growth factor receptor (EGFR), a member of receptor tyrosine kinase (RTK) family." (PMID 28388560, 2017). "Our previous studies have shown that the activity of EGFR can be modified by GALNT1 and GALNT2 in hepatocellular carcinoma and by GALNT2 in oral squamous cell carcinoma." (PMID 28388560, 2017).
breast carcinoma (4 papers, 2018 to 2023). "We investigated the association between GALNT1 expression and cell proliferation-related gene sets, which were significantly associated with breast cancer patient outcomes, as we had previously reported." (PMID 37444599, 2023). "Further, breast cancer with high GALNT1 expression was associated with less infiltration of CD8+ T cells, but not other immune cells." (PMID 37444599, 2023). "Although there was a report that high GALNT1 expression was significantly associated with decreased survival in breast cancer, this study used optimal cut-off and the results were not validated." (PMID 37444599, 2023). "As the number of drug therapies for breast cancer has been rapidly expanding in recent years, the association between GALNT1 expression and response for other drugs warrants further exploration, particularly for drugs that target angiogenesis or EMT." (PMID 37444599, 2023). "In older breast cancer patients, high GALNT1 expression was also significantly associated with a decreased amount of CD8+ T cells in both cohorts, however, the difference was smaller than that in AYA patients (p = 0.049 and = 0.002, respectively)." (PMID 37444599, 2023). "None of the hallmark cancer pathways, except for KRAS, were significantly enriched to high GALNT1 expression breast cancer by GSEA." (PMID 37444599, 2023). "Increased levels of GALNT1 expression in breast cancer amongst AYA patients enriched angiogenesis, EMT, and protein secretion but not in older patients." (PMID 37444599, 2023). "We found that breast cancer with high GALNT1 expression in AYA patients significantly enriched angiogenesis, EMT, and protein secretion gene sets, consistently in both the METABRIC and GSE96058 cohorts." (PMID 37444599, 2023). "In our current study, we investigated the clinical significance of GALNT1 expression in 5176 breast cancer patients from the METABRIC (n = 1903) and GSE96058 (n = 3273) cohorts using multiple computational algorithms." (PMID 37444599, 2023). "The GALNT family of genes have been associated with several cancer etiologies, such as the Tn antigen and epithelial-mesenchymal transition (EMT); however, the clinical significance of GALNT1 expression in breast cancer (BC) remains unclear." (PMID 37444599, 2023). "Although the role of GALNT1 in breast carcinogenesis is known, the clinical significance of its expression in breast cancer progression remains unclear." (PMID 37444599, 2023). "GALNT1 expression may have potential as a predictive biomarker amongst AYA patients with breast cancer." (PMID 37444599, 2023). "We cannot help but speculate that our findings on GALNT1 expression demonstrate its potential to become a predictive biomarker and a novel therapeutic target for breast cancer in the AYA generation." (PMID 37444599, 2023). "GALNT1 initiates O-glycosylation of glycoproteins; Sonic hedgehog protein (Shh), osteopontin, and MUC1, which contributes to the generation of breast cancer." (PMID 37444599, 2023). "Since it is well established that breast cancer in Adolescents and Young Adults (AYA: age less than 40 years old) is typically more aggressive than in older patients, it was of interest whether GALNT1 expression differed by age." (PMID 37444599, 2023). "In breast cancer, GALNT4, GALNT6, and GALNT8, have been reported to be associated with patient outcomes, whereas no other study examines the clinical role of GALNT1." (PMID 37444599, 2023). "Furthermore, we investigated the relationship between GALNT1 expression and other cells in the tumor microenvironment, including fibroblasts, microvascular and lymphatic endothelial cells, and pericytes, in AYA breast cancer." (PMID 37444599, 2023). "Since GALNT1 generates the Tn antigen that is widely reported to be predominantly expressed in cancer cells, there is clinical interest in investigating cellular expression levels in the tumor microenvironment (TME) of breast cancer patients, utilizing single-cell sequence cohorts." (PMID 37444599, 2023).
breast carcinoma (continued). "GALNT1 expression, which generates the Tn antigen, was associated with decreased infiltration of CD8 T cells, enhanced angiogenesis, EMT, and protein secretion, and was a prognostic biomarker for breast cancer in AYA patients, but not older patients." (PMID 37444599, 2023). "We found that GALNT1 expression was increased in triple-negative breast cancer (TNBC) and HER2-positive subtypes compared to ER-positive/HER2-negative BC, consistently in both cohorts, although this difference was minor." (PMID 37444599, 2023).
gastric cancer (4 papers, 2014 to 2022). A primary or metastatic malignant neoplasm involving the stomach. "Here, we show that the polypeptide N-acetylgalactosamine-transferase 1 (GALNT1) is frequently upregulated in gastric cancer and is correlated with poor survival." (PMID 36439876, 2022). "Overexpression of GALNT1 promoted, whereas knockdown suppressed proliferation, migration, and invasion of gastric cancer cells in vitro and in vivo." (PMID 36439876, 2022). "To investigate the potential role of GALNT family genes in gastric carcinoma (GC), we first analyzed the expression of GALNT1-20 in non-cancerous gastric mucosa using real-time RT-PCR." (PMID 26848976, 2016). "Collectively, this study demonstrates that GALNT1 overexpression in gastric cancer promotes the Wnt/β-catenin signaling pathway via abnormal O-glycosylation of CD44 to enhance malignancy, providing a novel strategy for the development of therapeutic reagents against gastric cancer." (PMID 36439876, 2022).
congenital heart disease (3 papers, 2015 to 2024). A heart disease that is present at birth. "Galnt1-knockout mice exhibit impaired cardiac valvulogenesis and compromised cardiac function that mimics human congenital heart disease, and is associated with reduced O-glycosylation on multiple proteins in heart valve tissues." (PMID 27281159, 2016). "In the adult mouse, compromised cardiac function that mimics human congenital heart disease, including aortic and pulmonary valve stenosis and regurgitation; altered ejection fraction; and cardiac dilation, was observed in Galnt1 null animals." (PMID 25615642, 2015).
lung carcinoma (3 papers, 2009 to 2024). "According to pervious report, GALNT1 is strongly associated with the using of tobacco and the risk of lung cancer." (PMID 19703314, 2009).
melanoma (3 papers, 2016 to 2018). A malignant, usually aggressive tumor composed of atypical, neoplastic melanocytes. "In A375 human melanoma cells exposed to kojic acid (a tyrosinase inhibitor and skin whitener), seven likely tumor-suppressor genes— GALNT1, APOBEC1, ARHGEF16, CD22, FGFR3, UNC5C and ZNF146— were shown to be down-regulated, resulting in the loss of suppressor gene function." (PMID 27322213, 2016).
cervical cancer (2 papers, 2015 to 2018). A primary or metastatic malignant neoplasm involving the cervix. "GALNT7 is frequently up-regulated in cervical cancer associated with cervical cancer cell proliferation, migration, and invasion; yet down regulation of GALNT1 and GALNT7 is associated with enhanced melanoma cell migration, invasion and immunosuppression." (PMID 25730904, 2015). "Moreover, GALNT1, and C1CAGLT1C, with higher expression in HeLa control cells, are reported to have medium and high expression levels in cervical cancer samples in this database, suggesting that viral oncoproteins could increase their expression in cervical cancer." (PMID 30038662, 2018).
lymph node metastasis (2 papers, 2022 to 2023). "We found that large tumors, lymph node metastasis, and high GALNT1 expression were all significantly associated with worse OS by univariate analysis in the AYA METABRIC cohort." (PMID 37444599, 2023). "Upregulated GALNT1 is associated with lymph node metastasis and distant metastasis, and GALNT1 can enhance the migration and invasion of GC cells in vitro." (PMID 36439876, 2022).
ovarian carcinoma (2 papers, 2011 to 2016). A malignant neoplasm originating from the surface ovarian epithelium. "In human, some nucleotide mutations of GALNT1 may cause ovarian cancer." (PMID 22174844, 2011). "The single-nucleotide polymorphism rs17647532 in GALNT1 was genotyped in fourteen studies to suggest association between GALNT1 alterations and ovarian cancer, but could not be confirmed in large populations." (PMID 27322213, 2016).
renal fibrosis (2 papers, 2022). A final common manifestation of a wide variety of chronic kidney diseases characterized by glomerulosclerosis and tubulointerstitial fibrosis. "In vitro experiments showed that the expression level of let-7i-5p was negatively correlated with GALNT1 and that overexpression of GALNT1 could inhibit inflammation induced by let-7i-5p, thereby suppressing the development of renal fibrosis in mice." (PMID 36429094, 2022).
Arthritis (1 paper, 2026). Inflammation of a joint. "Targeted suppression of GALNT1 effectively curtailed migration and invasion in RA FLSs and mitigated arthritis severity in a collagen-induced arthritis model in rats." (PMID 42024456, 2026).
bleeding disorder (1 paper, 2022). "However, later studies showed that GALNT1‐deficient mice exhibit a bleeding disorder and lack B‐cell maturation." (PMID 35334492, 2022).
colon cancer (1 paper, 2019). "Additionally, GALNT1 was the direct target gene of MIR216B, and SNHG7 could act as a ceRNA to sponge MIR216B, and rescue GALNT1 to facilitate colon cancer cell invasion." (PMID 31691514, 2019).
glioma (1 paper, 2008). A benign or malignant brain and spinal cord tumor that arises from glial cells (astrocytes, oligodendrocytes, ependymal cells). "Third, 1p19q codeleted gliomas were characterized by one specific cluster (gene cluster D) enriched in genes involved in CNS development (6 genes, p < 10-4), which also contained genes known to be specifically expressed in neuronal cells in the physiological state, e.g. DCX and GALNT1." (PMID 18492260, 2008).
Infertility (1 paper, 2021). "However, disruption of murine Galnt1 is not fatal and does not cause infertility, although Galnt1 deficiency does have moderate lethality and one-fourth of homozygous null mice, but not heterozygous mice, die in utero beyond E12.5 or before the age of one month for unknown reasons." (PMID 34576978, 2021).